WNT3A (Wnt family member 3A)
Diseases named in the same sentence as WNT3A in open-access papers (continued):
Sharing a sentence is not in itself a finding about the gene and the disease.
glioma (17 papers, 2015 to 2025). A benign or malignant brain and spinal cord tumor that arises from glial cells (astrocytes, oligodendrocytes, ependymal cells). "In addition, Wnt3a expression is associated with the clinical grade and aggressiveness of gliomas, and interestingly, it is overexpressed on glioma stem cells." (PMID 26369691, 2015). "Experiments in glioblastoma have shown that blocking canonical WNT signaling enhances CD4+/CD8+ immune cell infiltration in the TME, dramatically improving sensitivity to PD-1 therapy in gliomas while igniting ‘cold tumors’, suggesting that WNT3A may be a risk factor for immunotherapy." (PMID 36358276, 2022). "Varied expression levels of Wnt pathway components in gliomas have been observed, such as elevated WNT3A and 5A and decreased WNT7B, and the oncogenic role of overexpressed WNT6." (PMID 39874307, 2025). "In conclusion, CELSR2 positively regulates glioma development through WNT3A/β-catenin signaling and inhibiting CESLR2 is a novel therapeutic strategy for gliomas." (PMID 41184253, 2025). "WNT3A efficiently enhanced the proliferation of glioma cells and activated the downstream signaling, which were significantly compromised by CELSR2 knockdown." (PMID 41184253, 2025). "Taking together, we identify a novel signaling pathway-WNT3A/CELSR2/GSK-3β/β-catenin in the development of gliomas." (PMID 41184253, 2025). "In conclusion, our study demonstrates for the first time that CELSR2 promotes human glioma growth via the WNT3A/β-catenin pathway and administration of MNPs-loaded CELSR2-siRNA is a promising therapeutic strategy for gliomas." (PMID 41184253, 2025). "Peng at al reported that in addition to being upregulated in high-grade gliomas, CTHRC1 expression correlated with genes associated with the Wnt Signaling pathway (DVL3, DVL1, DVL2, ROR2, WNT3A, FZD6 and FZD5)." (PMID 36190948, 2022). "Overexpression of WNT1 and WNT3a in glioma stem cells has been shown in the malignant transformation and progression of high-grade gliomas, WNT2 and WNT5 are also overexpressed in glioma." (PMID 28620312, 2017). "Dysregulation of the Wnt canonical pathway leading to beta-catenin activation has been detected in glioma patients with overexpression of WNT3a and epigenetic-driven downregulation of inhibitors like SFRP1, Dkk1 or Wif1." (PMID 27613837, 2016). "As ligands that activate the Wnt/β-catenin signaling pathway, WNTs are widely implicated in the development of glioma, and clinical data show that expression levels of WNT5A, WNT3A and WNT1 are closely correlated with the overall survival of patients with glioma." (PMID 41184253, 2025). "The results suggest that CELSR2 KD compromises WNT3A induced glioma proliferation." (PMID 41184253, 2025). "Interestingly, glioma derived WNT3A has been reported to trigger an anti-inflammatory program in microglia, resulting in a less robust and more suppressed immune cell population." (PMID 38538643, 2024). "Wnt3a contributes to the chemoresistance of glioma-derived stem-like cells." (PMID 37509281, 2023). "Furthermore, miR-142-5p inactivates Wnt/β-catenin signaling via targeting Wnt3a, thus regulating the stem cell-like traits of glioma cells." (PMID 33509213, 2021). "Simultaneously, WNT3A-induced activation of the GSK-3β/β-catenin signaling and enhancement of cell cycle was significantly compromised in cultured CELSR2 KD glioma cells." (PMID 41184253, 2025). "In glioma cell culture, additional administration of WNT5A, WNT3A and WNT1 promoted cell proliferation, which is in line with the clinical report that high expression of WNT5A, WNT3A and WNT1 correlated with short OS of patients with gliomas." (PMID 41184253, 2025). "Our data demonstrate that CELSR2 promotes glioma growth through WNT3A/β-catenin signaling and inhibiting CELSR2 is a novel strategy for glioma therapy." (PMID 41184253, 2025). "Elevated expression of canonical Wnt factors (WNT3A, TCF4) correlates with higher glioma grades and poor outcomes." (PMID 39568072, 2024).
glioma (continued). "Inhibition of Wnt3a, but not Wnt4 or Wnt5a, attenuated cell growth and neural sphere formation in these PN glioma spheres." (PMID 27698350, 2016). "However, the enhanced glioma proliferation induced by WNT3A, but not by WNT5A or WNT1, was diminished by CELSR2 silencing." (PMID 41184253, 2025). "In vitro experiments demonstrate that glioma cell-derived Wnt3a triggers the activation of the Wnt/β-catenin pathway in microglia, induces them to express ARG-1 and STI1, shifts them to the M2 phenotype, enhances tumor infiltration, invasion, growth and the crosstalk between microglia and gliomas." (PMID 37700840, 2023).
glioblastoma (16 papers, 2014 to 2025). The most malignant astrocytic tumor (WHO grade IV). "ASCL1 has been shown to promote WNT signalling by directly repressing DKK1, a negative regulator of WNT signalling, and synergising with WNT3A to induce active WNT signalling in glioblastoma stem cells." (PMID 41287940, 2025). "In glioblastoma, breast and prostate tumors, and malignant mesothelioma, Wnt3a stimulates the development of cancer." (PMID 39200196, 2024). "The Wnt3a-stimulated glioblastoma cells, which can be seen as the result of overaction of the canonical Wnt pathway, show greater invasiveness than general glioblastoma and greater microglial infiltration when co-cultured with microglia." (PMID 32477095, 2020). "In addition, LEF1, β-catenin and Wnt3a as well as CD133 were found to be downregulated in iPSC-derived sFRP4 overexpressed glioblastoma cells compared to iPSC-GSCs." (PMID 37509281, 2023). "In recurrent glioblastoma (GBM) patients, the methylation levels of the promoters and genes of Wnt5a, β-catenin and Wnt3a are lower in comparison with the primary GBM patients." (PMID 38886806, 2024). "Similarly, both Wnt1 and Wnt3a support stem-like cells in glioblastoma multiforme (GBM)." (PMID 27355964, 2016). "In glioblastoma cells, NTSR1 expression is increased by the Wnt pathway activator Wnt3a and decreased by the Wnt inhibitor iCRT3." (PMID 39310276, 2024). "We further analyzed effects of 3 concentrations of clofazimine (5, 10, 15 μM) on the Wnt3a-induced response in the TopFlash assay in the panels of CRC, HCC, OC, and glioblastoma cell lines." (PMID 33363033, 2020).
neuroblastoma (11 papers, 2015 to 2021). Neuroblastoma (NB) is the most common solid, extracranial childhood tumor. "Considering that Ten-3 expression has also been linked to reduced neuroblastoma malignancy, we hypothesize that Wnt3a/Wnt5a-mediated Ten-3 expression might be associated with the Wnt3a/Wnt5a context-dependent protective effects against neuroblastoma." (PMID 31156379, 2019). "In our RNA-seq analysis of Wnt3a/Rspo2-treated neuroblastoma cells, BMP4 was amongst the most highly induced genes (>50-fold) and BMP4 protein was also upregulated, leading us to further analyse global effects of Wnt3a/Rspo2-treatment on BMP/TGF gene sets." (PMID 32210188, 2020). "Consistently with the convergence of Wnt and BMP signaling on MSX proteins, GSEA analysis confirmed a profound effect of Wnt3a/Rspo2 on the MSX1-regulated neuroblastoma transcriptome." (PMID 32210188, 2020). "First, the effect of DYRK1A kinase inhibition on LiCl or Wnt3a-driven Wnt signalling activity was investigated in a neuroblastoma (SH-SY5Y) cell line stably expressing a Wnt signalling luciferase reporter." (PMID 31086297, 2019). "These analyses, together with our evaluation of Wnt3a/Rspo2 effects on neuroblastoma cell biology, reveal that Wnt regulates recently discovered drivers of differentiation such as EPAS1 and BMP4 in cell lines that undergo differentiation." (PMID 29505958, 2018). "We also evaluated the effects of Wnt3a/Rspo2 treatment on a third LGR5-positive neuroblastoma cell line, SK-N-AS." (PMID 29505958, 2018). "This prompted us to define the neuroblastoma-specific Wnt3a/Rspo2-driven transcriptome using RNA sequencing, and characterise the accompanying changes in cell biology." (PMID 29505958, 2018). "Supporting the ITR analysis we have shown that recombinant Wnt3a protein alters neuroblastoma cell viability." (PMID 27531891, 2016). "However, our previous work demonstrated that Wnt3a/Rspo2 treatment of some neuroblastoma cell lines can, paradoxically, decrease c-MYC and MYCN proteins." (PMID 29505958, 2018). "Wnt3a triggers RhoA activity to regulate neurite retraction of mouse neuroblastoma cells." (PMID 28289332, 2017). "We confirmed that mitotic SH‐SY5Y neuroblastoma cells could detect a 2.5 ~ 5 × 10−3 nm·μm−1 Wnt3a concentration gradient and demonstrated that this gradient is sufficient to affect the determination of the pole‐to‐pole axis of cell division during the later stages of mitosis." (PMID 30524943, 2018). "We previously demonstrated that Wnt/β-catenin signaling can have cell-type-specific effects on neuroblastoma phenotypes, including growth inhibition and differentiation, and that BMP4 mRNA and protein were induced by Wnt3a/Rspo2." (PMID 32210188, 2020). "Based on our recent identification of genes regulated by the Wnt ligand Wnt3a and Wnt agonist R-spondin 2 in an NB cell-line, we assess transcriptional and signaling pathways, which require further investigation in the contexts of NC development and neuroblastoma." (PMID 31040767, 2019). "Analysis of genes that are increased with retinoic acid induced differentiation of neuroblastoma cells (NGRF, NF68, NTRK1, SYP, MAP2, NEFM, DKK2) showed that all were elevated after 72 hours Wnt3a/Rspo2 treatment." (PMID 29505958, 2018). "Moreover, zebrafish Nradd was able to significantly enhance apoptosis in human neuroblastoma SH-SY5Y cells, again independently of Wnt3a." (PMID 33466728, 2021). "Consistent with this, we did not observe any reporter activity with neuroblastoma cell lines in the absence of Wnt3a and R-spondin ligands." (PMID 26517508, 2015).
osteosarcoma (11 papers, 2013 to 2024). A usually aggressive malignant bone-forming mesenchymal neoplasm, predominantly affecting adolescents and young adults. "We guess that the specific mechanism of Wnt-3a/β-catenin pathway in osteosarcoma is inseparable from this contradiction, which also needs more research to explore and explain." (PMID 36551309, 2022). "Zinc exerted its anticancer effect by inhibiting the proliferation and invasion and promoting the apoptosis of osteosarcoma cells through activating the Wnt-3a/β-catenin signaling pathway." (PMID 32075661, 2020). "The results preliminarily verified that zinc activated the Wnt-3a/β-catenin signaling pathway of osteosarcoma cells and played an anti-cancer effect." (PMID 32075661, 2020). "To this end, we overexpressed PAWS1 in HEK293 human kidney cells and in U2OS osteosarcoma cells before stimulating with control or Wnt3A‐conditioned medium and measuring Wnt‐dependent TOPFlash luciferase reporter activity." (PMID 29514862, 2018). "We next determined the consequences of FHL2 silencing on osteosarcoma cell growth and survival in basal and Wnt3a-supplemented medium." (PMID 23383046, 2013). "DHRS12 inhibits osteosarcoma proliferation and metastasis via the Wnt3a/β-catenin pathway." (PMID 38212774, 2024). "Several studies have shown that this pathway participates in the regulation of proliferation and apoptosis of osteosarcoma cells; e.g., zinc inhibits the proliferation and promotes the apoptosis of osteosarcoma cells via the activation of the Wnt-3a/β-catenin signaling pathway." (PMID 36551309, 2022). "However, the anticancer effect and mechanism of zinc were preliminarily verified only by the change in proliferation and invasive abilities and by the expression of apoptotic proteins and Wnt-3a/β-catenin signaling pathway proteins in osteosarcoma cells." (PMID 32075661, 2020). "Results showed that zinc treatment significantly inhibited the proliferation and invasion of osteosarcoma cells, promoted cell apoptosis, increased the expression levels of Wnt-3a and β-catenin, marker proteins of the Wnt/β-catenin signaling pathway, in osteosarcoma cells." (PMID 32075661, 2020). "In addition, the expression levels of Wnt-3a and β-catenin, the marker proteins of the Wnt/β-catenin signaling pathways, were significantly increased in osteosarcoma cells after zinc intervention, which demonstrated that the pathway was clearly activated." (PMID 32075661, 2020). "Although FHL2 silencing abrogated the positive effect of Wnt3a on osteosarcoma cell growth, this effect might be explained by overall reduced proliferation since FHL2 silencing also abrogated FGF-2-induced cell proliferation." (PMID 23383046, 2013). "However, the specific role of the Wnt-3a/β-catenin pathway in osteosarcoma is still unclear." (PMID 36551309, 2022). "Besides, the expression levels of Wnt-3a and β-catenin proteins, the marker protein of Wnt/β-catenin signaling pathway, were also obviously promoted, which implied the Wnt/β-catenin signaling pathway was activated by zinc in osteosarcoma cells." (PMID 32075661, 2020). "U2OS osteosarcoma, FIB03 and FIB04 cells were incubated in the presence of control or Wnt3A conditioned medium for 6 h, and the expression of WNT target gene Axin2 was measured by qRT-PCR." (PMID 39043225, 2024). "This article addresses the study of osteopontin (OPN), WNT3A, and ABCB5 as biomarkers in osteosarcoma (OS) patients." (PMID 39239573, 2024). "The levels of Wnt3a, β-catenin and LEF1 in human osteosarcoma cells were significantly higher than those in embryonic osteoblasts." (PMID 33310972, 2020).
ovarian carcinoma (10 papers, 2015 to 2025). A malignant neoplasm originating from the surface ovarian epithelium. "Recently, Yamamoto and colleagues showed that olaparib-resistant ovarian cancer cells upregulate Wnt3A and that forced activation of the canonical Wnt/β-catenin pathway resulting in resistance to both olaparib and rucaparib." (PMID 39028933, 2024). "Our results show that Wnt3A upregulates canonical β-catenin targets in ovarian cancer cells with functional BRCA1 and BRCA2, particularly the full-length WT Tcf1/7, c-Myc, and cyclin D1." (PMID 39028933, 2024). "ILK silencing has also been shown to reduce the expression of wnt ligands (wnt3a, wnt4, and wnt5a) and β-catenin in epithelial ovarian cancer cells." (PMID 33256002, 2020). "To evaluate if a similar effect occurs in ovarian cancer cells, we used exogenous Wnt3A to activate the canonical Wnt pathway and assessed the effect of monensin on β-catenin signaling activity via nuclear staining." (PMID 26639992, 2015). "Interestingly, BRCA2-null mouse ovarian cancer cells demonstrated a unique response to Wnt3A with the preferential upregulation of the Wnt signaling inhibitor Axin2." (PMID 39028933, 2024). "Knocking down PYGB also significantly inhibited the expressions of Wnt3a, β-catenin, APC, and Cyclin D1 in ovarian cancer cells, suggesting that, through the Wnt/β catenin signaling pathway, PYGB might regulate the progression of ovarian cancer." (PMID 38334681, 2024). "Neither canonical nor noncanonical Wnt signaling was observed in BRCA2-null ovarian cancer cell in response to Wnt3A." (PMID 39028933, 2024). "Culturing dissociated single tumour cells in Matrigel with a cocktail medium of niche factors (WNT-3A, R-Spondin, etc.)enabled us to develop ovarian cancer organoids from different histologic subtypes (HGSC, EM, CCC) of stage I–III ovarian cancer patients within 1–3 weeks." (PMID 32724113, 2020). "In contrast to the activation of canonical Wnt signaling in ovarian cancer cells with functional BRCA1 and BRCA2, our results show that loss of BRCA1 leads to the activation of the noncanonical Wnt signaling pathway in response to Wnt3A." (PMID 39028933, 2024). "Interestingly, in our model, we observed that Wnt3A preferentially activates the noncanonical Wnt signaling pathway in BRCA1-null ovarian cancer cells." (PMID 39028933, 2024).
cervical carcinoma (9 papers, 2010 to 2025). A carcinoma arising from either the exocervical squamous epithelium or the endocervical glandular epithelium. "Here, we use HeLa cells, a human cervical cancer cell line, to demonstrate that localized Wnt3a signaling can direct spindle orientation even in a transformed, non-stem cell context." (PMID 41310344, 2025). "Our RT–PCR data also showed that DYNLT3 regulated the mRNA levels of Wnt3a in both cervical cancer cell lines." (PMID 35965516, 2022). "Specifically, TGFB1, WNT3A, and their targets are the top signaling pathway inhibited in immunotherapy responded cervical cancer." (PMID 34921236, 2021). "Methods: lnc-SNHG16, miR-128, GSPT1 and WNT3A expression were analyzed using quantitative real-time PCR and bioinformatics in cervical cancer tissues and cells." (PMID 32127947, 2020). "Overall, the total scores of Wnt3a, β-catenin and CBP immunoreactivity were significantly higher in CIN2/3 and cervical cancer tissues compared to the normal cervix and CIN1 tissues, respectively (p < 0.01)." (PMID 34257574, 2021). "Our present findings provide novel pathological insights into Wnt3a signaling in the progression of CIN and aggressiveness of cervical cancer, thus defining a potential therapeutic target for cervical lesions." (PMID 34257574, 2021). "Lastly, upregulation of CPT1A partially reversed the suppression of WNT3A, β-catenin, and c-Myc protein expression mediated by TM7SF2-knockout, suggesting that TM7SF2 regulated the WNT/β-catenin signaling via CPT1A in cervical cancer cells." (PMID 38693136, 2024). "In this study, the gene expression profile data showed that within the top 250 differentially expressed genes, the canonical Wnt signaling genes Wnt3a, β-catenin, and CBP were significantly upregulated in the CIN lesion and cervical cancer samples compared with those in the normal cervix sample." (PMID 34257574, 2021).